INTS9 (integrator complex subunit 9)
Description:
Component of the integrator complex, a multiprotein complex that terminates RNA polymerase II (Pol II) transcription in the promoter-proximal region of genes. The integrator complex provides a quality checkpoint during transcription elongation by driving premature transcription termination of transcripts that are unfavorably configured for transcriptional elongation: the complex terminates transcription by (1) catalyzing dephosphorylation of the C-terminal domain (CTD) of Pol II subunit POLR2A/RPB1 and SUPT5H/SPT5, (2) degrading the exiting nascent RNA transcript via endonuclease activity and (3) promoting the release of Pol II from bound DNA. The integrator complex is also involved in terminating the synthesis of non-coding Pol II transcripts, such as enhancer RNAs (eRNAs), small nuclear RNAs (snRNAs), telomerase RNAs and long non-coding RNAs (lncRNAs). Mediates recruitment of cytoplasmic dynein to the nuclear envelope, probably as component of the integrator complex.
Synonyms: Int9; RC-74; RC74; FLJ10871; CPSF2L
Tractability: PROTAC: UniProt records ubiquitination sites on it; ubiquitination databases record sites on it; its protein half-life has been measured.
Gene: Protein-coding gene on chromosome 8 (28,767,661 to 28,890,242, reverse strand). Ensembl gene ENSG00000104299.
Subcellular location: Nucleus; Cytoplasm
Subcellular location (Human Protein Atlas): Nucleoplasm
Pathways (Reactome):
Gene expression (Transcription): RNA polymerase II transcribes snRNA genes
Gene Ontology:
Molecular function: protein binding
Biological process: negative regulation of transforming growth factor beta receptor signaling pathway; regulation of transcription elongation by RNA polymerase II; RNA polymerase II transcription initiation surveillance; snRNA 3'-end processing; snRNA processing; negative regulation of transmembrane receptor protein serine/threonine kinase signaling pathway; regulation of cellular response to growth factor stimulus
Cellular component: cytoplasm; cytosol; INTAC complex; integrator complex; nucleoplasm; nucleus
Genetic constraint (gnomAD): Loss-of-function variants: 43 observed, 63.65 expected, observed/expected ratio (o/e) 0.68, 90% interval 0.53 to 0.87. The upper end of that interval is the gene's LOEUF score, 0.87, which puts it in group 3 of 6, group 1 being the genes least tolerant of losing a copy. Missense variants: 622 observed, 745.64 expected, observed/expected ratio (o/e) 0.83, 90% interval 0.78 to 0.89. Synonymous variants: 282 observed, 299.94 expected, observed/expected ratio (o/e) 0.94, 90% interval 0.85 to 1.04.
Homologues: Orthologues: macaque INTS9 (99% identical), rabbit INTS9 (99% identical), guinea pig INTS9 (98% identical), dog INTS9 (98% identical), rat Ints9 (97% identical), mouse Ints9 (97% identical), pig INTS9 (97% identical), chimpanzee INTS9 (92% identical), tropical clawed frog ints9 (90% identical), zebrafish ints9 (79% identical), Drosophila melanogaster IntS9 (51% identical), Caenorhabditis elegans ints-9 (30% identical). Paralogues in human: CPSF3 (19% identical), CPSF2 (17% identical), INTS11 (16% identical).
Diseases named in the same sentence as INTS9 in open-access papers:
INTS9 is named in the same sentence as 7 diseases in open-access papers, as found by Europe PMC text mining. Sharing a sentence is not in itself a finding about the gene and the disease. The quoted sentences say what the papers report.
astrocytomas (1 paper, 2023). "Our results showed that the combined chromosome 7 gain/10 loss and TERT promoter mutation associated with high INTS9 in the IDH wildtype astrocytoma during the CDKN2A/CDKN2B homozygous deletion in the IDH mutant glioma." (PMID 37537630, 2023). "In the immune cell components, we observed a positive correlation between myeloid cells and INTS9 expression in mutant astrocytoma but reversely associated with the dendritic cells in all subtypes." (PMID 37537630, 2023). "In contrast, in IDH wildtype astrocytoma, methylation of cg01124961, cg15720343, and cg23559680 led to the suppression of INTS9 expression, whereas methylation of cg04041942 positively correlated INTS9 expression." (PMID 37537630, 2023). "The status of CDKN2A/CDKN2B homozygous deletion linked to the INTS9 expression was found only in the IDH mutant glioma, including IDH mutant astrocytoma and oligodendroglia." (PMID 37537630, 2023). "Our findings indicated that INTS9 was significantly associated with increased M0 macrophages and monocyte reduction in both IDH wildtype astrocytoma and oligodendroglioma." (PMID 37537630, 2023). "A COX-survival analysis found that elevated INTS9 levels were significantly associated with a higher hazard ratio in IDH-wildtype and IDH-mutant astrocytoma, while only exhibiting a borderline association in oligodendroglioma." (PMID 37537630, 2023). "Our observations revealed that elevated INTS9 levels corresponded to the combined chromosome 7 gain/chromosome 10 loss status in IDH wildtype and mutant astrocytoma." (PMID 37537630, 2023). "In contrast, within IDH mutant astrocytoma, INTS9 demonstrated a significant correlation with M2 macrophages but no decrease in monocytes compared to other groups." (PMID 37537630, 2023). "We found that the reduction in INTS9 was linked to a decrease in tumor stem cells and proliferative tumor stem cells in IDH wildtype and only correlated with a decline in tumor stem cells in IDH mutant astrocytomas." (PMID 37537630, 2023). "In IDH mutant astrocytoma, INTS9 was associated with M2 macrophages without monocyte reduction." (PMID 37537630, 2023). "The heatmap of INTS9 expression demonstrated a strong correlation with tumor and myeloid lineages in both IDH wildtype and IDH mutant astrocytoma." (PMID 37537630, 2023). "A notable distinction among these subtypes is the inverse correlation between INTS9 and differentiated tumor cells in IDH mutant astrocytoma and oligodendroglioma; conversely, a positive correlation was identified in the IDH wildtype group." (PMID 37537630, 2023). "Our results revealed that INTS9 was significantly correlated with increased M0 macrophages and reduced monocytes in IDH wildtype astrocytoma and oligodendroglioma." (PMID 37537630, 2023). "To examine the potential impact of tumor heterogeneity on INTS9 expression, we analyzed two single-cell sequencing datasets, GSE131928 and GSE89567, which represent IDH wildtype and IDH mutant astrocytoma, respectively." (PMID 37537630, 2023). "Within the IDH mutant astrocytoma and oligodendroglioma groups, EPHA3 and NPAP1 surfaced as recurring genes potentially connected to the upregulation of INTS9." (PMID 37537630, 2023). "In terms of genomic stability, INTS9 displayed a positive correlation with TMB across all subgroups and a negative correlation with MSI in both astrocytoma groups, exhibiting a marginal association in oligodendroglioma." (PMID 37537630, 2023).
glioblastoma (1 paper, 2023). The most malignant astrocytic tumor (WHO grade IV). "Utilizing sophisticated screening approaches, the INTS9 has emerged as a promising candidate for glioblastoma therapeutics." (PMID 37537630, 2023).
glioma (1 paper, 2023). A benign or malignant brain and spinal cord tumor that arises from glial cells (astrocytes, oligodendrocytes, ependymal cells). "Our results found that increased INTS9 is associated with higher tumor proliferation, tumor grade, and poor prognosis in glioma." (PMID 37537630, 2023). "To achieve this, we employed an array of advanced bioinformatics analyses utilizing large-scale databases and conducted functional experiments using small interfering RNA targeting the INTS9 gene (siINTS9) to elucidate its involvement in glioma." (PMID 37537630, 2023). "The examination of bioinformatics data from the TCGA dataset demonstrated a significant elevation in INTS9 levels within the tumor compared to normal components across pan-glioma and all subgroups." (PMID 37537630, 2023). "This study assessed the role of INTS9 protein in glioma development and its potential as a therapeutic target." (PMID 37537630, 2023). "This investigation represents the inaugural study to uncover the involvement of INTS9 in glioma through the integration of comprehensive genomic (TCGA, CGGA), longitudinal analyses, single-cell, ATAC-sequencing datasets, and functional validation." (PMID 37537630, 2023). "In this investigation, our objective was to delineate the role of INTS9 in glioma." (PMID 37537630, 2023). "As a result, directing therapeutic strategies toward INTS9 could influence these cell populations and extend survival across all glioma subtypes, despite the IDH status." (PMID 37537630, 2023). "This research highlights the potential of INTS9 as a promising target for glioma treatment." (PMID 37537630, 2023). "Subsequently, we examined the dynamic alterations in INTS9 between primary and recurrent tumors utilizing the Glioma Longitudinal AnalySiS (GLASS) dataset, which comprises 423 samples, including 168 paired studies (130 IDH wildtype, 28 IDH mutant, and 10 oligodendrogliomas)." (PMID 37537630, 2023).
oligodendroglioma (1 paper, 2023). A well-differentiated (WHO grade II), diffusely infiltrating neuroglial tumor, typically located in the cerebral hemispheres. "Moreover, in the oligodendroglioma group, a correlation between INTS9 and the tumor proliferative stem cell component was only observed in primary tumors, not recurrences, possibly due to the limited sample size (n = 10) and significant tumor heterogeneity." (PMID 37537630, 2023). "Regarding the stromal cell components, INTS9 exhibited a trend of a negative association with oligodendrocytes, pericytes, and endothelial cells across all three subtypes but a positive correlation with fibroblasts, particularly in the IDH wildtype and oligodendroglioma." (PMID 37537630, 2023).
cancer (3 papers, 2017 to 2024). A tumor composed of atypical neoplastic, often pleomorphic cells that invade other tissues. "INTS9, INTS11, INTS13, and INTS14 were mutated in very few cancer types, with a very low mutation rate." (PMID 28468258, 2017). "However, no information has been available linking INTS9 with any cancer type." (PMID 37537630, 2023).
tumor (2 papers, 2023 to 2024). "In the expression data compared to the 12 cell states, we observed a positive association between INTS9 expression and tumor stem & proliferative stem cells, consistent with previous analyses using TCGA and CGGA datasets." (PMID 37537630, 2023). "Earlier bioinformatics characterization and functional validation of INTS9 revealed a correlation between tumor grade and proliferative function." (PMID 37537630, 2023). "Our research indicates a robust correlation between INTS9, tumor stem cells, and proliferative states within the tumor." (PMID 37537630, 2023). "The findings indicated an increased expression of INTS9 in tumor cells instead of normal brain lysates, corroborating previous bioinformatics investigations." (PMID 37537630, 2023). "In the context of the 12 cell states, INTS9 correlated with tumor-stem and tumor-proliferative-stem cells." (PMID 37537630, 2023). "Consistent with the transcriptome findings, INTS9 protein expression was significantly elevated in tumor components compared to normal." (PMID 37537630, 2023). "Then, we also investigate the impacts of tumor heterogeneity on INTS9 expression by integrating single-cell sequencing, 12-cell state prediction, and CIBERSORT analyses." (PMID 37537630, 2023). "In both groups, our findings revealed a connection between higher INTS9 Immunoscore and increased tumor grades." (PMID 37537630, 2023). "Within the tumor components, we observed a positive correlation between INTS9 and tumor-stem cells and tumor-proliferative-stem cells across all three subtypes and various databases." (PMID 37537630, 2023). "Initially, we ascertained the presence of INTS9 in various tumor cell lines, such as U87MG, U118MG, LN229, LNZ308, and GBM8401." (PMID 37537630, 2023). "These aspects could collectively influence INTS9 expressions, leading to a more complex interaction with various potential variables than the primary tumor state." (PMID 37537630, 2023). "Additionally, the decrease in INTS9 was positively associated with an increase in oligodendrocytes and occasionally with pericytes and endothelial cells, which are the INTS9 cold cellular components, contrasting with the tumor and myeloid lineage cells that exhibit high INTS9 expression." (PMID 37537630, 2023). "Our findings showed increased INTS9 levels in tumor tissue compared to non-neoplastic components, correlating with high tumor grading and proliferation index." (PMID 37537630, 2023).
INTS9 also shares sentences with these, for which no sentence is quoted: aniridia (1 paper).